CD96 (CD96 molecule)
Description:
May be involved in adhesive interactions of activated T and NK cells during the late phase of the immune response. Promotes NK cell-target adhesion by interacting with PVR present on target cells. May function at a time after T and NK cells have penetrated the endothelium using integrins and selectins, when they are actively engaging diseased cells and moving within areas of inflammation.
Synonyms: TACTILE
Tractability: Antibody: its Gene Ontology location is reachable by antibodies, with high confidence; UniProt predicts a signal peptide or a membrane-spanning region. PROTAC: ubiquitination databases record sites on it.
Gene: Protein-coding gene on chromosome 3 (111,292,719 to 111,665,996, forward strand). Ensembl gene ENSG00000153283.
Subcellular location: Membrane
Pathways (Reactome):
Immune System: Immunoregulatory interactions between a Lymphoid and a non-Lymphoid cell
Gene Ontology:
Molecular function: protein binding
Biological process: cell-matrix adhesion; cell adhesion; immune response
Cellular component: cytoplasm; plasma membrane; membrane
Genetic constraint (gnomAD): Loss-of-function variants: 13 observed, 17.81 expected, observed/expected ratio (o/e) 0.73, 90% interval 0.47 to 1.16. The upper end of that interval is the gene's LOEUF score, 1.16, which puts it in group 5 of 6, group 1 being the genes least tolerant of losing a copy. Missense variants: 193 observed, 197.46 expected, observed/expected ratio (o/e) 0.98, 90% interval 0.87 to 1.1. Synonymous variants: 65 observed, 69.99 expected, observed/expected ratio (o/e) 0.93, 90% interval 0.76 to 1.14.
Gene-disease validity (ClinGen):
ClinGen rates the evidence that CD96 causes each of these diseases.
C syndrome (autosomal dominant): Limited. C syndrome is a rare multiple congenital anomaly/intellectual disability syndrome characterized by trigonocephaly and metopic suture synostosis, dysmorphic facial features, short neck, skeletal anomalies, and variable intellectual disability.
Homologues: Orthologues: chimpanzee CD96 (98% identical), macaque CD96 (92% identical), dog CD96 (74% identical), pig CD96 (71% identical), guinea pig CD96 (67% identical), mouse Cd96 (61% identical), rat Cd96 (61% identical), rabbit CD96 (59% identical), zebrafish si:ch1073-15f19.2 (9% identical).
Diseases named in the same sentence as CD96 in open-access papers:
CD96 is named in the same sentence as 97 diseases in open-access papers, as found by Europe PMC text mining. Sharing a sentence is not in itself a finding about the gene and the disease. The quoted sentences say what the papers report.
glioma (25 papers, 2019 to 2024). A benign or malignant brain and spinal cord tumor that arises from glial cells (astrocytes, oligodendrocytes, ependymal cells). "CD96 has already been clearly associated with the prognosis of human hepatocellular carcinoma, advanced ovarian cancer, and glioma." (PMID 35223835, 2022). "High CD96 expression is associated with poorer overall and disease-specific survival in low-grade gliomas." (PMID 35909123, 2022). "Our results demonstrate that CD96 expression was significantly linked with immune functions in glioma." (PMID 32612110, 2020). "CD96 has been reported as a novel immune checkpoint in glioma and associates with immune cell infiltration." (PMID 33363022, 2020). "CD96 expression was increased in malignant phenotype and negatively associated with overall survival in glioma." (PMID 32695752, 2020). "The results indicated that CD96, age, gender, WHO grade, IDH mutation, and h1p19q codeletion status were closely associated with OS and revealed that CD96 is an independent prognosticator for glioma patients." (PMID 32695752, 2020). "Increasing findings showed that CD96 served for the diagnosis and treatment of patients with skin cutaneous melanoma, glioma, and cervical cancer." (PMID 37306828, 2023). "ALKBH5 expression showed positive association with ICP receptors such as TNFRSF14, CD40, CD96 and CD200R1, and ICP ligands such as PDCD1LG2, CD70, TNFSF14, ICOSLG and CD274 in glioma tissues." (PMID 35444654, 2022). "Especially, high CD96 expression was associated with poorer overall survival (OS) and disease-specific survival (DSS) in the TCGA lower grade glioma (LGG) cohort (OS, HR = 2.18, 95% CI = 1.79–2.66, P < 0.001)." (PMID 33680972, 2021). "Overall, our comprehensive study of the molecular and clinicopathological features of CD96 through 1,001 samples will provide a better understanding of CD96 in glioma and pave the way for developing CD96-targeted cancer immunotherapies." (PMID 32695752, 2020). "Eventually, we evaluated the independence of the clinicopathological significance of CD96 in glioma by univariate and multivariate Cox regression analyses." (PMID 32695752, 2020). "To make a systematic examination of CD96 in glioma, we gathered RNA-seq and clinical data for 325 glioma samples from the Chinese Glioma Genome Atlas (CGGA) project." (PMID 32695752, 2020). "Subsequent gene ontology analysis of both datasets suggested that genes relevant to CD96 are mainly involved in immune functions in glioma as such genes were positively correlated with CD96 expression." (PMID 32612110, 2020). "We extracted and analyze RNA-seq data from TCGA and CGGA datasets to find out the expression pattern of CD96 in gliomas." (PMID 32612110, 2020). "Herein, we probed the biological functions of CD96 in glioma through large scale and in-depth analyses." (PMID 32695752, 2020). "Subsequent GO analysis suggested that genes most relevant to CD96 were mainly involved in immune functions in gliomas and that immune genes were significantly positively correlated with CD96 expression." (PMID 32612110, 2020). "The area under the curve (AUC) was 89.5% and 78.6% for TCGA and CGGA datasets, respectively and these results indicated that CD96 can serve as a potential biomarker for the mesenchymal-molecular subtype of glioma." (PMID 32612110, 2020). "We also discovered that higher CD96 expression predicted worse survival rates in glioma and GBM patients." (PMID 32695752, 2020). "To fully understand the relationship between CD96 and T cell-related immunity in glioma, we performed GSVA to assess differential activities of pathways between sets of genes." (PMID 32695752, 2020). "Univariate and multivariate Cox analysis demonstrated that CD96 acts as an independent indicator of poor prognosis in glioma." (PMID 32695752, 2020).
glioma (continued). "Considering that CD96 expression was closely tied to malignancy, we inferred that CD96 became an integral part of glioma progression and therefore performed GO analysis to uncover its role." (PMID 32695752, 2020). "In summary, our study is the first to explore the expression and clinical characteristics of CD96 in gliomas." (PMID 32612110, 2020). "Based on the TCGA dataset and CGGA dataset, our results showed that CD96 expression was much higher in mesenchymal-molecular subtype glioma, compared to that in the other three subtypes." (PMID 32612110, 2020). "Our findings indicate that CD96 is a promising clinical target for further immunotherapeutic use in glioma patients." (PMID 32695752, 2020). "Gene ontology enrichment and gene set variation analysis analyses suggested that CD96 was mostly involved in immune functions and was especially related to T cell-mediated immune response in glioma." (PMID 32695752, 2020). "Higher CD96 expression is associated with worse OS in patients with WHO grades II, III, and IV glioma based on data from the CGGA dataset (respectively)." (PMID 32695752, 2020). "Owing to the high relevance between CD96 and immune suppressor in glioma, the prognostic impact of CD96 was verified via the Kaplan–Meier method." (PMID 32695752, 2020). "Our results also indicated that CD96 checkpoint-related immune responses were more prevalent in IDH-wildtype glioma." (PMID 32612110, 2020). "Overall survival (OS) analysis in glioma patients demonstrated that high expression of CD96 predicted relatively poor survival in the CGGA and TCGA cohorts." (PMID 32695752, 2020). "Future research is needed to further explore multi-checkpoint blockade combined with CD96 inhibitors for glioma treatment." (PMID 32612110, 2020). "Subsequent analysis in TCGA dataset indicated that CD155 was positive associated with CD96, CD226, and Nectin4 in glioma and GBM samples." (PMID 31377744, 2019). "In glioma, CD96 is a significant immune checkpoint with a unique role in modulating the TME." (PMID 38342925, 2024). "There has been less research done on the role of CD96 in glioma." (PMID 36674817, 2023). "Univariate and multivariate Cox analysis showed CD96 as an independent predictor in glioma." (PMID 36674817, 2023). "Thus, in various cancers, especially gliomas and melanomas, CD96 is a potential biomarker to determine patient immune infiltration and prognosis." (PMID 35909123, 2022). "In addition to that, they discovered that higher CD96 expression predicted worse survival rates in glioma and GBM patients overall." (PMID 34305910, 2021). "The subtype analysis revealed contrary expression distributions of CD96 in glioma and melanoma." (PMID 33680972, 2021). "This intriguing difference suggested that CD96 mediated immunosuppressive effects in glioma patients, but participated in completely opposite immune processes in melanoma patients, highly indicating that CD96 impacted patient prognosis via an immune-related manner." (PMID 33680972, 2021). "Our results highlighted that CD96 may be a promising biomarker and therapeutic target for glioma that presents favorable application prospects." (PMID 32695752, 2020). "We inferred that collaboration of CD96 with other checkpoint members, especially PD-1, may increase glioma immunotherapy effectiveness." (PMID 32695752, 2020). "Moreover, CD96 is a promising immunotherapy target that positively collaborates with other checkpoint proteins in glioma." (PMID 32612110, 2020). "We thus aimed to genetically and clinically characterize CD96 expression in gliomas." (PMID 32612110, 2020). "The results revealed that CD96 expression was comparatively upregulated in higher-grade gliomas." (PMID 32695752, 2020). "CD96 expression was markedly enriched in higher-grade malignant pathological gliomas." (PMID 32695752, 2020). "We further analyzed the transcript levels of CD96 in different glioma subtypes." (PMID 32612110, 2020).
glioma (continued). "Firstly, the expression level of CD96 in gliomas can be affected by tumor purity." (PMID 32612110, 2020). "Moreover, we believe that a better understanding of CD96 in glioma will help to further develop cancer immunotherapies." (PMID 32612110, 2020). "We carried out ROC curves analysis of CD96 expression and mesenchymal subtype in glioma." (PMID 32695752, 2020). "ROC curves analyses of CD96 in glioma of all WHO grades were next conducted." (PMID 32695752, 2020). "Collectively, CD96 exhibited a malignant biological property in glioma." (PMID 32695752, 2020). "Our study explored the relationship between CD96 expression and clinical prognosis in glioma." (PMID 32695752, 2020). "This significant prognostic signature implied that CD96 blockade may significantly improve the prognosis of glioma patients, especially GBM patients." (PMID 32695752, 2020). "The distribution of CD96 in different glioma subtypes was next analyzed." (PMID 32695752, 2020). "This implied that CD96 blockade may significantly improve the prognosis of glioma patients." (PMID 34305910, 2021). "CD96 participates in diverse immune responses, governs immune cell infiltration, and impacts malignant properties of various cancer types, thus standing as a potential biomarker for determining patient prognosis and immune infiltration in multiple cancers, especially in glioma and melanoma." (PMID 33680972, 2021). "Moreover, CD96 was found to predict worse survival for glioma and GBM patients." (PMID 32612110, 2020). "Moreover, it will be necessary to further explore our hypothesis by examine CD96 protein level using large sample size to confirm the important role of CD96 in gliomas." (PMID 32612110, 2020). "Therefore, the prognostic value of CD96 were analyzed through these two glioma datasets." (PMID 32612110, 2020). "The immune permeability testing results showed a strong correlation between CD96 and the infiltration levels of CD4+ T cells, CD8+ T cells, neutrophils, macrophages, and dendritic cells in low-grade gliomas and glioblastoma multiforme." (PMID 36674817, 2023). "In general, most immune checkpoints (including PD-1, TIM-3, CD96, PDCD1, IDO1, PDCD1LG2, and CTLA-4) were highly expressed in glioma cells." (PMID 36778644, 2023). "For example, ICP gene CD96 had 259, 257, 225, 191 and 157 cooperative lncRNAs in THYM, UVM, Testicular Cancer (TGCT), Pancreatic Cancer (PAAD) and Lower Grade Glioma (LGG)." (PMID 37770497, 2023). "The results demonstrated higher CD96 expression in higher WHO grade, IDH-wildtype, and mesenchymal-subtype gliomas." (PMID 32612110, 2020). "CD96 expression was significantly up-regulated in high-grade, IDH-wildtype, and mesenchymal-molecular subtype gliomas based on TCGA data, which was validated using the CGGA dataset." (PMID 32612110, 2020). "In the TCGA dataset, CD96 expression in glioblastoma (WHO IV) was higher than in WHO grade II and grade III glioma in TCGA." (PMID 32695752, 2020). "CD96 had a consistently positive relationship with glioblastoma and was highly enriched in IDH-wildtype and mesenchymal subtype glioma." (PMID 32695752, 2020). "CD155 showed strong positive concordance with CD96, CD226, and Nectin4 in all gliomas and GBM samples from Rembrandt dataset." (PMID 31377744, 2019). "Interestingly, two bioinformatics-based studies revealed that CD96 was significantly expressed in citrate dehydrogenase (IDH) wild-type and mesenchymal subtype gliomas and positively correlated to glioblastoma." (PMID 36674817, 2023). "Our study showed RS was interconnected with CD16, CD226, CD96 and CD112, which could activate NK cells to kill glioma cells to achieve prolonged survival." (PMID 35236310, 2022). "Moreover, glioma cells express increased levels of immunosuppressive factors such as PD-L1, TIGIT, CD96, and CTLA-4, which negatively regulate presentation of antigens and T-cell responses." (PMID 35281049, 2022).
glioma (continued). "Our results show that CD96 is a negative prognostic marker in glioma and plays an important role in the immune response." (PMID 32612110, 2020). "We found that CD96 expression was significantly higher in higher grade gliomas; when compared to that in WHO grade II and grade III gliomas, WHO grade IV glioma (glioblastoma) showed the highest expression, and the results were consistent in both TCGA dataset and CGGA dataset." (PMID 32612110, 2020). "CD96 expressed higher in higher grades of glioma in TCGA and CGGA datasets, indicating CD96 could be a potential malignant biological indicator in glioma." (PMID 32612110, 2020). "Therefore, we hypothesized that high ALKBH5 expression altered the immune microenvironment in the glioma tissues by modulating the expression levels of ICP receptors and ligands such as TNFRSF14, CD40, CD96, PDCD1LG2, CD70 and TNFSF14." (PMID 35444654, 2022). "Hence, we investigated whether CD96 expression was connected with immune infiltration levels in GBM (glioblastoma multiforme) and LGG (Low-Grade Glioma) by using TIMER website tools." (PMID 32695752, 2020). "Furthermore, CD96 shows strong concordance with other immune checkpoint proteins such as TIGIT, CD226, and CRTAM, as well as established markers including PD-L1, CTLA-4, TIM-3, and STAT3, suggesting its potential for synergistic antitumoral effects in glioma immunotherapy​​." (PMID 38342925, 2024). "However, there has been no integrative investigation of CD96 in glioma." (PMID 32695752, 2020). "However, upon review of the related literature, we could not find any comprehensive reports of CD96 expression in glioma." (PMID 32612110, 2020).
melanoma (22 papers, 2019 to 2024). A malignant, usually aggressive tumor composed of atypical, neoplastic melanocytes. "In addition, for TIGIT/CD96 signaling pathway, most of the related genes were shown to have high expression levels in low risk melanoma patients." (PMID 34040608, 2021). "The expression of CD96 is upregulated in melanoma, and the protein is also found to be expressed by NK cells and CD8+ T cells, capable of further tuning the activity of these cells." (PMID 38893071, 2024). "The use of mouse CD96 antibodies is shown to significantly inhibit the growth of colorectal cancer, melanoma, and subcutaneous fibrosarcoma in mice, a mechanism independent of NK cells and requires the involvement of CD8+ T cells and IFN-γ." (PMID 36674817, 2023). "Mice studies found that blocking CD96 can reduce lung metastasis of melanoma cells by controlling NK cell activity and IFN-γ production." (PMID 36674817, 2023). "In lung cancer, prostate cancer, and melanoma mouse models, CD96 inhibition was shown to inhibit tumor metastases." (PMID 37046787, 2023). "Augmented NK cell function in CD96-/- mice is best exemplified by improved antimetastatic activity in B16F10 melanoma, RM-1 prostate cancer, and EO771 breast cancer models." (PMID 35812451, 2022). "But in certain studies, CD96 was less expressed in breast cancer, colorectal cancer, gastric cancer, and leukemia, lymphoma, melanoma, and sarcoma." (PMID 33680972, 2021). "MICA, NT5E/CD73 and tactile/CD96 showed statistically significant increase in melanoma patients vs. HDs." (PMID 30761123, 2019). "Contradictorily, another study showed increased serum levels of soluble CD96 in NK cells from late-stage melanoma patients." (PMID 31681269, 2019). "Finally, we explore the impact of CD155 and its receptors DNAM-1, TIGIT, and CD96 on immune cells, especially in the context of the melanoma tumour microenvironment and anti-cancer immunotherapies." (PMID 38893071, 2024). "Using bioinformatic research tools, it was shown that CD96 expression was lower in rectal cancer, melanoma, and fibrosarcoma compared to paraneoplastic tissue, which implies that CD96 could promote CD8+ T cell activation as a co-stimulatory receptor." (PMID 36674817, 2023). "Although the abnormal expression of CD96 has been reported to participate in carcinogenesis in many human types of cancer, the bioinformatics role of the CD96 in melanoma is unknown." (PMID 36043142, 2022). "Oncomine data showed increased levels of CD96 in brain, breast, and kidney cancers and leukemia relative to normal tissues, while in several datasets, CD96 levels were lower in breast, colorectal and gastric cancers, as well as in leukemia, lymphoma, melanoma, and sarcoma." (PMID 33680972, 2021). "Furthermore, CD96−/− mice are resistant to MCA-induced fibrosarcoma and experimental lung metastasis modeled by injecting B16F10 melanoma cells, and blocking CD96 with a mAb inhibits experimental metastases in three different models (B16F10 melanoma, 3LL lung carcinoma, and RM-1 prostate cancer)." (PMID 31681269, 2019). "Regarding the role of CD96 in the regulation of T cell functionality, tumor growth is better controlled by CD96-negative CD8+ T cells compared to CD96-positive CD8+ T cells in murine models of colon cancer, melanoma, and fibrosarcoma." (PMID 37629138, 2023). "Of note, GIMAP7 mRNA expression displays impressive correlations with immune checkpoints PDL2, CD96, TIGIT, BTLA, other immune checkpoints in melanoma, and across 30 cancer types." (PMID 36588164, 2023). "According to the melanoma SCRS data, all mir-149 targets identified were expressed in lymphocytes, some of which were exclusively expressed in this cell type and include CD96, CD48, SLAMF7, FASLG, NUGGC and NLRC5." (PMID 32024530, 2020).